HDAC6 (histone deacetylase 6)
Diseases named in the same sentence as HDAC6 in open-access papers (continued):
Sharing a sentence is not in itself a finding about the gene and the disease.
tumor (continued). "Furthermore, present molecular and biochemical data suggest that, once hydrolyzed, ST7612AA1 acts both in nucleus and cytoplasm of the target tumor cell, through HDAC6 inhibition, as observed for other HDACi of the hydroxamate class." (PMID 25671299, 2015). "Moreover, H292 xenografts with HDAC6 depletion displayed smaller tumor weight and volume, as well as increased basal apoptosis compared with control xenografts." (PMID 22957056, 2012). "The influence of HDAC1 and HDAC6 on tumour aggressiveness is controversial." (PMID 18671804, 2008). "This suggests that HDAC6 inhibition could be a strategy to target tumour metabolism indirectly." (PMID 40721560, 2025). "Notably, an in vivo study employing animal models demonstrated that combining HDAC6 inhibition via ACY1215 with ICIs constitutes a potential therapeutic approach for ARID1A-mutated OCCC, effectively limiting tumor progression through a cytotoxic T-cell-dependent mechanism." (PMID 41383608, 2025). "In addition, an interesting link exists between HDAC6, and lipid metabolism in tumor cells." (PMID 41458974, 2025). "In addition, class I HDACs and HDAC6 (class IV) are crucial for the formation of tumor immunity." (PMID 39935431, 2025). "As HDAC6 is involved in the regulation of immune responses, HDAC6 inhibitors have shown the potential to improve antitumor immunity by increasing the immunogenicity of tumor cells, augmenting immune cell activity, and alleviating immunosuppression in the tumor microenvironment." (PMID 38258065, 2023). "Moreover, it was reported that HDAC6 affects the Hsp90-mediated regulation of VEGFR in tumor cells." (PMID 38258065, 2023). "Moreover, HDAC6 inhibitors improve the therapeutic efficacy of anti-PD-1 immunotherapy by reducing the number of anti-inflammatory M1 macrophages and downregulating the expression of immune checkpoints such as PD-L1 in tumor cells." (PMID 36270986, 2022). "Second, although we determined that HDAC6 expression levels were associated with tumor immune cell infiltration and patient survival, we could not directly demonstrate that HDAC6 affects patient survival through immune infiltration." (PMID 34485153, 2021). "In addition, the study has demonstrated that HDAC6 could regulate the tumor progression by suppressing the signaling pathway of canonical Wnt/β-catenin in HCC." (PMID 33622179, 2021). "Also, the K–M survival curve indicated that HDAC6 was a prognostic indicator of tumor DSS." (PMID 34485153, 2021). "Meanwhile, the negative-regulation of HDAC6 in human HCCs and consequential loss of its tumor suppression ability supported by previous research apparently advocate the hypothesis." (PMID 32878239, 2020). "Thus, inhibiting HDAC6 has the potential to increase anti-tumor immunity." (PMID 32103105, 2020). "Our initial working hypothesis stated that targeting HDAC6 enzymatic activity could improve the therapeutic effect of anti-PD-1 by decreasing the up-regulation of immune-suppressive mediators such as PD-L1, PD-L2, B7-H3, and B7-H4 in tumor cells." (PMID 30992475, 2019). "Therefore, we investigated whether genetic HDAC6 inactivation would impair tumor growth by HDAC6 silencing in the Notch3-dependent cell line TALL1." (PMID 29643474, 2018). "Therefore, overexpression of HDAC6 has been related to tumor cells invasion and metastasis." (PMID 29593536, 2018). "So, HDAC6 inhibition in A549 cells might improve quisinostat anti-tumor activity." (PMID 27423454, 2016). "In this context, HDAC6 is frequently overexpressed in GBM and contributes significantly to tumor progression." (PMID 40843669, 2025).
tumor (continued). "By reprogramming immune cells and increasing the expression of PD-L1 on tumor cells, HDAC6 inhibition enhances the antitumor activity of CD8 + T cells and amplifies immune responses, creating a more favorable tumor microenvironment." (PMID 40057667, 2025). "Consistent with the subcutaneous model, knockdown of HDAC6 and USP9X notably suppressed GBM tumor growth and reduced Ki‐67 and GS expression in the intracranial model." (PMID 40162736, 2025). "Tub A, a selective HDAC6 antagonist, exhibits low neurotoxicity and multimodal efficiency: it suppresses pro-inflammatory cytokines (TNF-α and IL-6), restores tumor-suppressive primary cilia, and inhibits viral RNA synthesis." (PMID 41135681, 2025). "Encouraging data sustain the clinical use of either selective HDAC6 inhibitors or DGAT inhibitors as anti-tumor agents." (PMID 41458974, 2025). "BKS-112 regulated α-tubulin acetylation and decreased HDAC6 expression in MDA-MB-231 cells, resulting in reduced tumor growth and invasiveness compared to SAHA." (PMID 41300448, 2025). "Therefore, HDAC6 may be correlated to the tumour aggressiveness and progression." (PMID 39941046, 2025). "The J22352 compound promotes the degradation of aberrantly expressed HDAC6 in GBM, with the consequent autophagic-dependent cell death, block of cell migration, and tumour growth inhibition in mouse subcutaneous xenografts." (PMID 39595195, 2024). "Further, by Sp1 deacetylation and the consequent increased transcriptional activity, HDAC6 regulates endoglin, a co-receptor activating transforming growth factor-β (TGF-β) signal transduction, expression and tumour angiogenesis." (PMID 39595195, 2024). "Given their specific roles in tumor development and progression, as well as their unique structural characteristics, HDAC4 and HDAC6 have been identified as promising targets for the development of multi-target HDAC/ROCK inhibitors." (PMID 39458584, 2024). "Not only does RASSF1A act as a tumor suppressor through DNA repair, but RASSF1A has also been found to increase microtubule stability through HDAC6, which prevents tumor cell migration, invasion, and metastasis." (PMID 38279330, 2024). "Here, we discovered that histone deacetylase 6 (HDAC6)-selective inhibitors not only increased proteasome activity but enhanced antigen presentation and promoted CTL-mediated tumor lysis." (PMID 38747592, 2024). "High-throughput screens revealed that histone deacetylase 6 (HDAC6) inhibitors activated proteasomes to unmask neoantigens and amplify the tumor-specific antigenic landscape." (PMID 38747592, 2024). "In our comprehensive analysis of HDACs in DLBCL patients using public databases, we found that the expression levels of HDAC1, HDAC2, HDAC3, HDAC6, HDAC7, HDAC8, and HDAC9 were higher in tumor tissues compared to normal control for the first time." (PMID 38168914, 2024). "HDAC6 is a member of the HDAC family that is mainly located in the cytoplasm and promotes tumor cell migration and invasion through deacetylation of α‐tubulin and cortactin, which destabilizes the cytoskeleton." (PMID 38334007, 2024). "The oncogenic potential of HDAC6 has been well established in CRC as its inactivation by genetic manipulation reduced oncogenic transformation and tumor growth in in vitro as well as in vivo models." (PMID 38258065, 2023). "IL-6 has been reported to induce the expression of HDAC6, concomitantly with increased proliferation, migration, and EMT of tumor cells." (PMID 38258065, 2023). "The overexpression of HDAC6 in CRC, its role in promoting tumor growth through regulation of the MAPK/ERK signaling pathway, and its effect on patient survival indicate the oncogenic potential of HDAC6 in this malignancy." (PMID 38258065, 2023).
tumor (continued). "The leading compound is the HDAC6 inhibitor, which acts via the hyperacetylation of MYC (K148ac), strongly inducing its proteasomal degradation via the parallel sensitization of tumor cells to ionizing radiation." (PMID 37443779, 2023). "The first in vivo evidence of the potential of PROTACs as anticancer agents for GB was provided by a recent work in which the authors exploited the ability of a high-selective histone deacetylase 6 (HDAC6) inhibitor, J22352, to impair GB tumor growth." (PMID 35242765, 2022). "A ChIP-seq analysis showed a clear decrease in H3K27ac at the HDAC6 locus in LIPG knockdown tumor cell models, indicating that LIPG epigenetically mediates tumor cell metabolism through chromatin modifications." (PMID 35954428, 2022). "The Class IIb member, HDAC6, even exhibited contradictory activities to HDAC5 in the regulation of tumor immunity." (PMID 35265200, 2022). "Another study described that the HDAC6 inhibitor ACY-241 alone, and when combined with Oxaliplatin (chemotherapy drug), promoted T cell functions, thereby increasing the immunogenicity of tumor cells, in an NSCLC mouse model." (PMID 36012642, 2022). "As one mechanism of LIPG in the regulation of tumor cell oxidative metabolism, LIPG mediates histone deacetylase 6 (HDAC6) and histone acetylation, which contribute to changes in IL-6 and fatty acid synthesis gene expression." (PMID 35954428, 2022). "For instance, HDAC6 recruited and activated STAT3, enabling an upregulation of PD-L1, and the treatment of HDAC6 specific-inhibitors leads to retard tumor growth and downmodulate PD-L1 expression in vivo." (PMID 34365463, 2021). "Individual tumor samples were analyzed by R package (ESTIMATE), and the relationship between HDAC6 expression levels and immune score, stromal score, and the immune score of ESTIMATE was analyzed separately." (PMID 34485153, 2021). "In Chronic lymphocytic leukemia (CLL), the combination of HDAC6 inhibitor (ACY-738) with PD-L1 blockage using monoclonal antibodies significantly increased anti-tumor efficiency of T-cells and reduced tumor burden." (PMID 34200679, 2021). "HDAC6 deacetylates PTEN at K163 and promotes the membrane translocation of PTEN, which activates tumor suppressing function of PTEN." (PMID 33860796, 2021). "High HDAC-2 and HDAC-6 expression levels were more frequently observed in malignant thyroid tumors, with HDAC -1, -4 and -6 being correlated with tumor size." (PMID 34441281, 2021). "HDAC6 is a unique member of the HDAC family that can regulate cell proliferation, metastasis, and invasion in tumors, and can also drive tumor progression and confer drug resistance in some cancers." (PMID 34040090, 2021). "In non-small cell lung cancer, a combination of a HDAC6 inhibitor Riclinostat and JQ1 reduced tumor growth though diminishing Treg and increasing T cell and DC activity." (PMID 33859645, 2021). "With regard to tumor suppressor MST1, a component of the Hippo pathway, HDAC6‐mediated deacetylation induced its degradation through chaperone‐mediated autophagy." (PMID 32755037, 2020). "More directly, Cullin 3SPOP has been reported to destabilize HDAC6 via polyubiquitination, and this interaction has suggested that SPOP serves a tumor suppressor function through this mechanism." (PMID 33020410, 2020). "Compound 23BB as a highly selective and potent HDAC6 inhibitor with the IC50 of 17 nM has been synthesized and evaluated against anti-tumor activity in our laboratory." (PMID 31894849, 2020).
tumor (continued). "In addition to the effect of the abrogation of HDAC6 on the expression of immunosuppressive proteins, it has been shown that the genetic and enzymatic inhibition of HDAC6 induces the expression of MHC class I as well as several tumor- associated antigens including gp100, MART1, TYRP1, and TYRP211." (PMID 30992475, 2019). "These early reports align with the findings reported here; demonstrating a pivotal role of HDAC6 in controlling the inflammatory environment in the TME, tilting the balance to a pro-inflammatory landscape and favor anti-tumor immune responses." (PMID 30992475, 2019). "Here we show by western blot and IHC analysis that HDAC6 localizes to both the nucleus and cytoplasm of CRC cells and patient-derived tumor tissues." (PMID 30804456, 2019). "As a first-in-class selective HDAC6 inhibitor, ACY-1215 has been reported to have the effect to regulate cell apoptosis in tumor." (PMID 31244662, 2019). "It has been also demonstrated that the normal function of this tumor suppressor miRNA is to down-regulate a number of putative oncogenes including validated miR-22 targets MAX, MYCBP, HDAC4, HDAC6, CDK6, CDKN1A and NCoA1." (PMID 29716630, 2018). "Therefore, inhibition of HDAC6 in these tumours might result in undesired side effects." (PMID 29716651, 2018). "A HDAC6-specific inhibitor called KA2507, inhibits tumor growth through regulation of aggresome formation, and inhibition of PD-L1 expression via decrease of STAT3 phosphorylation." (PMID 30096875, 2018). "One of the HDAC6 inhibitors, ACY-1215 (ricolinostat), is currently in multiple clinical trials for evaluation of its anti-tumor activity (NCT01997840, NCT02091063, NCT02632071, NCT01583283, NCT02189343, NCT02787369)." (PMID 30270813, 2018). "In particular, the inhibition of tubulin deacetylation mediated by two identified tubulin deacetylases HDAC6 and SIRT2 enhances sensitivity to the anti-motility activity of paclitaxel theoretically potentiating the anti-tumor effect of the drug." (PMID 28423567, 2017). "In a previous report it was observed that, in addition to HDAC1/2, HDAC6 is also upregulated in SHH-MB and its targeting leads to a substantial anti-tumor effect in mouse models of SHH-MB29." (PMID 28276480, 2017). "HDAC6 plays an important role in tumorigenesis, invasion and metastasis, whereas SPOP has been shown to be a well-characterized tumor suppressor." (PMID 28599312, 2017). "Intriguingly, phosphorylated MIIP protects deacetylation of RelA from HDAC6, thereby ensures EGFR-stimulated RelA transcriptional activity and potentiates tumor metastasis." (PMID 29038521, 2017). "We also show that K-ras can induce HDAC6 expression by a MAP kinase dependent pathway, and that SAHA suppresses c-myc expression and tumor growth in K-ras transformed cells." (PMID 26848526, 2016). "Using mouse models with subcutaneous tumor xenografts grown from implanted A375 cells, we observed smaller tumors from A375 cells expressing ShRNA against HDAC5 or HDAC6." (PMID 26747087, 2016). "Of note, we found that mimicking GRP78 acetylation by substituting the lysine at residue 633, one of the deacetylated sites of HDAC6, with a glutamine resulted in decreased GRP78 secretion and impaired tumour cell growth in vitro." (PMID 27460191, 2016). "We demonstrate that both HDAC6 and c-myc are induced by an activated K-ras mutant and inhibition of HDAC6, either by HDAC6 siRNA or SAHA, blocks K-ras induced c-myc expression and tumor growth." (PMID 26848526, 2016). "To further study whether the HDAC6 score was influenced by the different composition in molecular subtypes between IBCs and non-IBCs we evaluated the HDAC6 score after stratifying the tumor series based on their hormone receptor (HR) status and their intrinsic molecular subtype." (PMID 26643555, 2015).
tumor (continued). "We further demonstrate that normal function of this tumor suppressor microRNA is to down-regulate a number of putative oncogenes including validated miR-22 targets MAX, MYCBP, HDAC4, HDAC6, CDK6, and NCoA1." (PMID 26244872, 2015). "A similar analysis in BRCA1 vs BRCA2 tumours highlighted increase in PPI co-expression around the mitotic regulators CDK1, CDC20 and CKS1B and the histone deacetylases HDAC1 and HDAC6; these are known drug targets for which inhibitors have been developed." (PMID 25521701, 2014). "Treatment with ibrutinib plus ACY1215, a selective histone deacetylase 6 (HDAC6) inhibitor, produced a direct synergistic antitumor effect in MCL tumor cell lines accompanied by a 3-fold increase in induction of apoptosis." (PMID 23958373, 2013). "To investigate the effect of HDAC6 knockdown on tumor growth in vivo, we injected H292-pRS or H292-HD6KD cells into nude mice and analyzed the tumor development by xenograft." (PMID 22957056, 2012). "In CRC, HDAC6 expression is elevated in tumor tissue relative to adjacent non-cancerous tissue and is frequently linked to poor disease prognosis." (PMID 40521202, 2025). "Simultaneously, HDAC6 has been shown to downregulate cyclin-dependent kinase inhibitor 1A (p21) expression by inhibiting SMAD2 phosphorylation, thereby attenuating TGF-β receptor signaling and facilitating tumor growth." (PMID 40450300, 2025). "Furthermore, HDAC6 overexpression was reported to be more pronounced in metastatic lymph nodes (MLNs) of ESCC and, to a lesser extent, in the primary tumour." (PMID 39941046, 2025). "Interestingly, a newly published study identified histone deacetylase-6 (HDAC6) as a promising therapeutic target, showing that its inhibition can reduce inflammation and alter the tumour microenvironment in a way that limits OSCC progression." (PMID 41440367, 2025). "HDAC6 deacetylates PTEN at K163, promoting interaction between the PTEN C‐terminus and the rest of the protein and inhibiting its membrane translocation, thus inactivating PTEN and promoting tumour growth." (PMID 39778006, 2025). "As an inhibitor of histone deacetylase 6 (HDAC6), WT161 exerts anti-tumor effects by enhancing the acetylation of histones H3 and H4 on the promoter of the apoptosis-related gene BAD, prompting cell apoptosis and evoking anti-tumor responses." (PMID 38920989, 2024). "HDAC6 is widely known for deacetylating particular cytosolic non-histone substrates involved in tumor genesis, progression, and metastasis." (PMID 39409979, 2024). "The correlation between HDAC6 expression and the prognosis of RCC patients was investigated in a previous study involving 45 fresh RCC samples and 132 paraffin-embedded tissues, along with their corresponding adjacent non-tumor tissues." (PMID 39063958, 2024). "Interestingly, when HDAC6 inhibitor (ACY1215) was combined with meticrane, a significantly high impact on the viability of tumor cells (K562, Jurkat and SK-hep-1) were observed." (PMID 37274234, 2023). "Subsequently, the acetylated GRP78 dissociates from HDAC6 and then binds to VPS34, a class III PI3K, thus preventing the sorting of GRP78 into multivesicular bodies and GRP78 release that induces its aggregation in the ER that further inhibits tumor growth." (PMID 38258065, 2023). "Zhang Y. and coauthors hypothesized that dual inhibition of HDAC6 and PAK1 could have strong implications for tumor treatment by simultaneously targeting oncogenic metabolic pathways and epigenetic modification." (PMID 38004560, 2023).